CXCR3 (C-X-C motif chemokine receptor 3)
Diseases named in the same sentence as CXCR3 in open-access papers (continued):
Sharing a sentence is not in itself a finding about the gene and the disease.
tumor (continued). "Collectively, dual inhibition of FGFR4 and CXCR3 suppressed tumor growth in vivo, which was accompanied by CAF suppression and immune modulation in TME." (PMID 40447617, 2025). "As the disease progresses, elevated systemic levels of CXCL10 overwhelm the localized chemokine gradient at the primary tumor site, creating a potent immune decoy that diverts anti-tumor CXCR3+ T cells away from the tumor." (PMID 41516196, 2025). "This aligns with evidence that CXCR3-associated T-cell trafficking is crucial for anti-tumor immunity and that CXCR3 is required for CD8+-T-cell tumor homing." (PMID 40696453, 2025). "Due to the critical role of CXCR3 and its ligands in various diseases, CXCR3 has emerged as a promising target for anti-tumor and anti-inflammatory therapies." (PMID 40786052, 2025). "CXCL10, which binds to CXCR3 on activated T cells and promotes their directional trafficking, is a major factor driving the attraction of T cells to tumor sites." (PMID 40025520, 2025). "This high systemic concentration establishes a chemokine gradient that functions as an immune decoy, actively misdirecting CXCR3+ tumor-specific immune cells away from the primary tumor." (PMID 41516196, 2025). "T-bet+ hTregs influence CD8+ T cell activation in the tumor-draining lymph node, although this effect appears to be unrelated to CXCR3 activity." (PMID 41041322, 2025). "Previous research has indicated that CXCR3 regulated tumor migration, differentiation and exocytosis." (PMID 40781073, 2025). "The CXCL-9, −10, −11/CXCR3 axis promotes tumor suppression through the recruitment of cytotoxic lymphocytes, NK cells, and NK T cells in a paracrine manner." (PMID 40447617, 2025). "In NSCLC, the expression of CXCR3 and its ligands is elevated within the tumor microenvironment (TME), influencing the activity of natural killer (NK) cells and T cells, which are critical for the surveillance and elimination of cancer cells." (PMID 40786052, 2025). "The administration of the recombinant IL-7 protein reduced tumor burden with extensive lymphocytic infiltration of the tumor and enhance survival through the CXCR3 signaling pathway in lung cancer-bearing mice." (PMID 40707961, 2025). "Specifically, CR scores (based on CXCR6, CXCR3 and CCR5 expression) were not only associated with significant differences between these tumor types but also linked to improved overall survival uniquely within brisk tumors." (PMID 41415437, 2025). "CXCR3 exhibits a dual role, either inhibiting tumor growth by blocking angiogenesis or promoting metastasis through chemotaxis." (PMID 40445003, 2025). "CXCL9 and CXCL10 are induced by IFN-γ secreted from activated T cells and establish chemotactic gradients to recruit CXCR3+ CD8+ T cells to tumor niches." (PMID 40698080, 2025). "Recent studies on anti-PD1 monotherapy have demonstrated that CXCL9 and CXCL10 were crucial, since its receptor CXCR3 was found to be the arbitrator for the PD-1+ CD8+ T cells infiltration in B16 murine melanoma tumours." (PMID 40852716, 2025). "In in-vivo experiments, we used a blocking antibody against CXCR3 to demonstrate a reduction in the tumor control efficacy of the MEKi+RT combination treatment, which, in turn, was associated with decreased T-cell infiltration." (PMID 41368644, 2025). "In murine breast cancer models, aerobic exercise delayed tumour growth by increasing CXCR3-dependent signaling that promotes T cell infiltration to tumours." (PMID 40951642, 2025). "Mechanistically, CXCL10 from the stroma activates CXCR3 on tumor cells and stimulates downstream signaling pathways such as MAPK/ERK and PI3K/Akt, leading to cytoskeletal reorganization, enhanced cell survival and targeted migration." (PMID 40760734, 2025). "Since the CXCR3-CXCL9 axis plays a critical role in tumor infiltration and reinvigoration of CD8+ T cells in response to PD-1 blockade, we next examined the role of CXCL9 and CXCR3 in mediating the anti-tumor effects of DB using the B16-OVA tumor model." (PMID 40867314, 2025).
tumor (continued). "The effects of the CXCL9/CXCL10/CXCL11-CXCR3 axis can vary, even within the same organ, depending on the distribution of CXCR3 subtypes in tumor cells." (PMID 40362215, 2025). "Genetic deletion of CXCR3 in Tregs led to a marked increase of cDC1‐mediated cross‐presentation of tumour antigens to CD8+ T cells in the TME." (PMID 40878038, 2025). "Tumor-infiltrating CD4+ T28zT2 T cells exhibited phenotypes of memory-like T cells with high CXCR3 expression." (PMID 40107245, 2025). "At the same time, the inhibition of CXCR3 had an anti-tumor effect in this model, similar to our observations." (PMID 40362215, 2025). "These CXCR3+-T-cells clustered more frequently in tumor cell-rich (PanCK+) regions, suggesting active immune-mediated tumor killing." (PMID 40696453, 2025). "Treatment of PyMT-OVA tumor-bearing mice with CXCR3 blocking antibodies abolished the iCoup-mediated increase in T cell frequency." (PMID 40796746, 2025). "Ablation of the TGF-β receptor I (ALK5) restores CXCR3 expression, enhances T cell infiltration and cytotoxicity, and promotes tumor regression, these effects are partially reversed by CXCR3 blockade." (PMID 41268548, 2025). "Treatment with BLU9931, an FGFR4 inhibitor, attenuated tumor progression, and co-treatment with the CXCR3 inhibitor AMG487 further enhanced this inhibitory effect, highlighting the synergistic function of the two inhibitors." (PMID 40447617, 2025). "For example, the imbalance between chemokine receptor CXCR3 expressed by TILs that traffic CTL to the TME and CXCL9/CXCL10 (ligands of CXCR3) up-regulated by tumor cells leads to inefficient recruitment of CTL to the tumor." (PMID 40292310, 2025). "In contrast, ELR-negative chemokines such as CXCL9, CXCL10, and CXCL11 are classically viewed as anti-tumor agents due to their angiostatic and immune modulatory effects mediated by their shared receptor, CXCR3." (PMID 41516196, 2025). "Studies have shown that oral administration of Akkermansia muciniphila can increase the recruitment of CCR9+CXCR3+CD4+ T lymphocytes to the tumor bed, thereby restoring the efficacy of PD-1 inhibitors in NSCLC patients." (PMID 40406244, 2025). "CXCR3 is directly or indirectly involved in tumor progression by regulating tumor growth, migration, invasion, angiogenesis, and immunity." (PMID 40786052, 2025). "On the one hand, CXCL9/CXCR3 promotes anti‐tumor immunity by attracting CXCR3+ cytotoxic lymphocytes to the tumor microenvironment, which can inhibit tumor growth." (PMID 40145607, 2025). "Reg-1 KO CAR T cells expressed higher levels of chemokine receptors (Cxcr3, Cxcr6) that orchestrate tumor-reactive T cell infiltration and function." (PMID 40475601, 2025). "The mosaic COUP-TFII induction experiments suggest that iCoup autonomously induces EC expression of CXCL10, a chemokine that attracts T cells expressing CXCR3, which also proved necessary for the enhanced T cell recruitment and tumor inhibition." (PMID 40796746, 2025). "For instance, CXCL9/10 secreted by DC1s establish chemotactic gradients that guide CXCR3+ CD8+ T cells to tumor niches, while their co-expression with CCL5 amplifies T cell infiltration and correlates with improved survival in solid tumors." (PMID 40698080, 2025). "To elucidate the mechanistic role of CXCR3, we conducted transcriptomic profiling of tumor xenografts, revealing that CXCR3 depletion would disrupt mitochondrial homeostasis." (PMID 40185710, 2025). "CXCL9, an IFN-γ-inducible chemokine that recruits CXCR3+ effector T and NK cells, is central to anti-tumor immunity." (PMID 41357226, 2025). "Their study elucidates that LDRT recruits stem cell-like progenitor exhausted CD8+ T cells (CD8+ Tpex) from draining lymph nodes to the tumor site via the CXCL10/CXCR3 axis, enhancing the sensitivity of tumors to DPVB and achieving tumor regression." (PMID 40317077, 2025).
tumor (continued). "In lung cancer, CXCR3 promotes tumor progression by regulating the expression levels of receptors on inflammatory cells or the expression levels of ligands on tumor cells." (PMID 40786052, 2025). "The chemokine receptors CCR6, CCR7, CXCR3, CXCR4, CXCR5, and CXCR6 have the highest expression across lymphocytes, and CCR8, a known hallmark of tumour infiltrating Treg cells, is exclusively expressed on Treg cells." (PMID 39915477, 2025). "The use of small molecule CXCR3 antagonists has demonstrated significant efficacy in OS models, markedly reducing tumor cell migration in vitro and substantially inhibiting the development of lung metastases in vivo." (PMID 41516196, 2025). "Previous studies have reported that CXCL10/CXCR3 signaling is required for T cell tumor infiltration and tumor immunotherapy." (PMID 40315321, 2025). "Compared to the WT group, the absence of tumor growth inhibition and induced T cell infiltration, alongside the larger tumor size in CXCR3 KO mice, underscores that this chemokine pathway is indispensable for the observed immune-mediated antitumor function." (PMID 41463372, 2025). "On the other hand, the canonical role of CXCL10 is to act as a potent chemoattractant for anti-tumor immune cells, including activated T cells and natural killer (NK) cells, via its receptor CXCR3 within the TME." (PMID 41516196, 2025). "In ‎cancers where CXCL10 inhibits angiogenesis and metastasis, targeting the CXCL10/CXCR3 ‎axis is a promising strategy to effectively ‎suppress tumor growth." (PMID 40760734, 2025). "The interaction between chemokines such as CXCL9, CXCL10, CXCL11, and their receptor CXCR3 is known to affect immune cell behavior, potentially enhancing tumor growth and spread." (PMID 39964621, 2025). "Monoclonal antibodies against CXCL10 and inhibitors of CXCR3 significantly reduced T cell count of both eosinophil-tumor coculture group." (PMID 40025520, 2025). "There are two common isoforms of the CXCR3 receptor, CXCR3 A and CXCR3 B. Overall, CXCR3 is associated with cancer progression by altering the TME, but also with anti-tumor effects and growth reduction in vivo." (PMID 40362215, 2025). "Regorafenib treatment increases tumor infiltration of CD8+CXCR3+ T cells and inhibits tumor growth by upregulating C-X-C motif chemokine ligand 10 (CXCL10) expression in HCC cells, thereby improving survival rates." (PMID 40317077, 2025). "Simultaneously, imiquimod causes peripheral lymphocytes to express CXCR3, a homologous chemokine receptor that causes CD4+ T cells to infiltrate and accumulate within the tumor and is crucial for tumor rejection." (PMID 40727443, 2025). "In this regard, we demonstrated that the CCR7→ CXCR3 switch was significantly decreased in RARα‐TG CTLs in tumor‐draining lymph nodes." (PMID 40068101, 2025). "A vigorous CXCR3+-T-cell response at primary diagnosis in tumor tissues therefore appears to predict also a better outcome in the advanced treatment situation." (PMID 40696453, 2025). "Key members of the chemokine family, CXCL9, CXCL10, and CXCL11, bind to their shared receptor CXCR3 to regulate immune cell differentiation, directional migration, and tumor infiltration." (PMID 40574854, 2025). "Oncolytic adenovirus carrying CXCL10 significantly inhibits tumor growth and prolongs survival by continuously secreting CXCL10 and recruiting CD8+ T cells and NK cells expressing CXCR3 to the core tumor area." (PMID 41425703, 2025). "It was evident that IRF‐score is strongly associated with multiple chemokines and receptors in 12 tumours, in particular CCL5, CCR2/4/5, CXCL9/10/11 and CXCR3 (p < 0.05)." (PMID 38130025, 2024). "We also examined the expression of chemokine receptors involved in tumor trafficking, CXCR3 and CCR5, in CD44+PD-1+ CD8 T cells from TDLNs." (PMID 39763661, 2024).
tumor (continued). "Our findings showed that high expression of CD8+ T cells, CXCR3 in tumor-infiltrating lymphocytes (TILs), and an inflamed phenotype were associated with better recurrence-free survival (RFS)." (PMID 39409972, 2024). "The immunological changes induced by A. muciniphila and E. hirae in mice included the promotion of IL-12 secretion by dendritic cells and the accumulation of CCR9+ CXCR3+ CD4+ T cells in the tumour microenvironment." (PMID 39634265, 2024). "Specifically, the complex formed by IL-7 with IL-7R-Fc has been shown to induce an anti-tumour response by increasing the infiltration of T cells into tumours through the CXCR3 chemokine signalling pathway." (PMID 38675377, 2024). "Conversely, tumor-derived CXCL10 can interact with CXCR3 to induce tumor cell proliferation, angiogenesis, and other pro-tumorigenic effects." (PMID 38720149, 2024). "For example, in the MC38 tumor model used in this study, a 6.7-fold increase in CXCR3+ T cell density was observed after ICI therapy." (PMID 39196448, 2024). "CXCL9 and CXCL10 (CXCL9/10) signal through C-X-C motif chemokine receptor 3 (CXCR3) to promote the tumor infiltration of CXCR3+ effector T cells, including type 1 T helper (Th1) cells and CD8+ cytotoxic T lymphocytes." (PMID 38518770, 2024). "Studies indicate that NK cells possess the capability to efficiently migrate to tumor sites through chemokine signaling, with C-X-C Motif Chemokine Receptor 3 (CXCR3) playing a particularly crucial role in the localization of NK cells into tumors." (PMID 39633491, 2024). "The upregulated genes in PTCL‐TBX21 included Th1‐related genes, including CXCR3, CD38, INFG, CXCL9, CXCL11, IL27, and genes associated with tumor immunity, such as CD274 (PD‐L1), LAG3, and IDO1." (PMID 38234210, 2024). "Only the administration of CXCL10-Fc to mice transferred with CXCR3+ CD8+ T cells led to a significant decrease in tumor size." (PMID 39474427, 2024). "We inoculated wild-type (WT) or CXCR3 KO mice with B16F10 tumor cells and administered CD3xTRP1 at an early timepoint (day six and nine)." (PMID 38167722, 2024). "While only 3.4 ± 1.9% CXCR3+ cells were detected in the untreated MC38 tumor tissues, two cycles of therapy cycles led to a significant increase in CXCR3+ cells (9.7 ± 2.8%)." (PMID 39196448, 2024). "CXCL9/10/11 are interferon-induced chemokines that recruit effector CD8+ and CD4+ T cells to the tumor microenvironment by binding them to their cognate receptor CXCR3." (PMID 38928238, 2024). "Strikingly, addition of aCD73 to 5FU+OHP + aPD-L1 significantly upregulated CXCR3 in the CT26 tumor microenvironment." (PMID 38206570, 2024). "For example, CXCL9 and CXCL10 are two important chemokines that are involved in antitumor immunity by binding to their receptor, CXCR3, which promotes the migration of T cells and NK cells into the tumor microenvironment." (PMID 39334957, 2024). "Among different chemokine receptors examined, we found CXCR3 significantly increased expressed on CD8+ T-cells in the tumour." (PMID 38271469, 2024). "For lymphoid cells, we found an increased expression of the cytokine receptors CCR6 and CXCR3 in memory T cells from both benign disease and tumor patients." (PMID 38686549, 2024). "Treatment of mice bearing KPL-3M tumors intraperitoneally (i.p.)with CXCR3 blockade enhanced tumor growth compared to the isotype control." (PMID 38518770, 2024). "Despite significant therapy-induced changes in specific uptake of [64Cu]Cu-NOTA-α-CXCR3 in the spleen and lymph nodes, limitations were encountered with respect to imaging changes in CXCR3+ T cell infiltration or CXCR3 upregulation on tumor-resident T cells." (PMID 39196448, 2024). "In a mouse tumor model, the suppressive effect of CD8+ T cells on tumor growth was dependent on CXCR3 expression." (PMID 39543650, 2024). "Cxcl10 and its receptor, Cxcr3, as well as granzyme A (Gzma) and granzyme B (Gzmb) levels, which support an activated T cell responses, were elevated in CR705Parp7KO tumours." (PMID 39867896, 2024).
tumor (continued). "The CXCL9 and CXCL10/CXCR3 axes play two roles in the tumor environment: paracrine signaling for immune activation and autocrine signaling for cancer proliferation and metastasis." (PMID 38720340, 2024). "Accordingly, specific chemokines, such as CXCR3 and its ligands, have been shown to directly mediate antitumor immunity, thereby inhibiting tumor development and increasing survival." (PMID 39769501, 2024). "In contrast, in patients with high tumor burden (> 50%) the number of CXCR3 + T cells decreased in PB, while an increased number of CXCR3 + T cells was observed in the BM, suggesting a tumor-load dependent migration of inflammatory T cells to the BM." (PMID 39613747, 2024). "A previous study examining the impact of specific DPP4 inhibition in murine cancer models has demonstrated that DPP4 inhibition not only elevates tumor CXCL10 levels but also enhances the trafficking of CXCR3+ NK cells and CD8+ T cells into tumors." (PMID 38672409, 2024). "Here, we show that pre-treatment vaccination, even when composed of tumor-unrelated antigens, induces CXCR3-mediated T-cell influx in immunologically ‘cold’ tumor models in male mice." (PMID 38167722, 2024). "In a study using irradiated EBV-LCL feeder cells with IL-2, the increased expression of CXCR3 by NK cells led to improved homing and tumor-killing activity against CXCL10-transfected melanoma xenograft mice." (PMID 39339180, 2024). "Blocking CXCR3 has been shown to improve NK cells’ infiltration in the bone marrow and reinforce IL-15-activated NK cells’ anti-tumor activity." (PMID 38475811, 2024). "Again, treated tumors show increased and more homogenous infiltration than untreated tumors, where CXCR3+ cells are mainly localized on the outer rim of the tumor." (PMID 39196448, 2024). "In the H group, there were also a few specific interactions, such as the interactions between the dendritic cell-expressed ligands CCR6 and CXCR3 with the tumor cells-expressed receptor CCL20." (PMID 39268081, 2024). "Among these are CX3CR1 and CXCR3, which play pivotal roles in the homing of NK cells to peripheral tissues, including tumor sites." (PMID 39563446, 2024). "Through the facilitation of the recruitment of CCR9+CXCR3+CD4+ T lymphocytes to the tumor tissue in mice, AKK bacteria can initiate an antigen-specific T cell response." (PMID 38617841, 2024). "Cxcr3, a chemokine receptor with anti-tumor effects expressed in effector CD8+ T cells, Th1 cells, and NK cells, interacts with its ligands Cxcl9, Cxcl10, and Cxcl11, promoting immune cell recruitment to TME." (PMID 38622609, 2024). "CXCR3 is expressed on activated T cells and plays a crucial role in T-cell recruitment to the tumor microenvironment (TME) during cell-based and immune checkpoint inhibitor (ICI) immunotherapy." (PMID 39196448, 2024). "Preclinical evidence demonstrates that the injection of B16F10 tumor cells with decreased CXCR3 expression into C57BL/6 mice greatly decreases the occurrence of metastasis in lymph nodes." (PMID 39273452, 2024). "It is well established in the literature that T cell function as well as infiltration into the tumor is strongly dependent on CXCR3." (PMID 39196448, 2024). "Single-cell RNA-sequencing analysis of patient tumor-infiltrating lymphocytes revealed that CXCR3 was expressed by CD8+ and CD4+ T cells, whilst CXCL9 and CXCL10 were predominantly expressed by macrophages following dual ICI treatment." (PMID 38533720, 2024). "IFNγ induces macrophages to produce more CXCL9 and CXCL10, two chemokines that bind to CXCR3 on the surface of T cells and promote their recruitment for anti-tumor immune response." (PMID 38787372, 2024). "IFNγ-inducible chemokines CXCL9 and CXCL10 are ligands for CXCR3, a receptor expressed by diverse immune populations and reported to play important roles in immune cell recruitment and tumor immunity." (PMID 38454126, 2024).